RPS27AP11 (RPS27A pseudogene 11)
Synonyms: RPS27A_4_740
Gene: Processed pseudogene on chromosome 6 (113,581,501 to 113,581,947, forward strand). Ensembl gene ENSG00000218208.
Diseases named in the same sentence as RPS27AP11 in open-access papers:
RPS27AP11 is named in the same sentence as 1 disease in open-access papers, as found by Europe PMC text mining. Sharing a sentence is not in itself a finding about the gene and the disease. The quoted sentences say what the papers report.
cancer (1 paper, 2021). A tumor composed of atypical neoplastic, often pleomorphic cells that invade other tissues. "In addition, RPS27AP11 was significantly expressed in more than 10 cancer types, so RPS27AP11 was also in the first category." (PMID 34869316, 2021). "Although there is no report about RPS27AP11, relevant research has been sufficient to indicate the indispensable regulatory mechanism of pseudogenes in cancers." (PMID 34869316, 2021).